LRRK2 (leucine rich repeat kinase 2)
Diseases named in the same sentence as LRRK2 in open-access papers (continued):
Sharing a sentence is not in itself a finding about the gene and the disease.
inflammatory bowel disease (60 papers, 2012 to 2026). A spectrum of small and large bowel inflammatory diseases of unknown etiology. "Mutations in leucine-rich repeat kinase 2 (LRRK2) are known risk factors for both PD and inflammatory bowel disease (IBD), suggesting a link between PD and the gastrointestinal tract." (PMID 40883285, 2025). "Subsequently, LRRK2 mutations were also discovered to be linked with inflammatory bowel disease (IBD), cancer, leprosy, etc.." (PMID 38607004, 2024). "In this sense, Lrrk2 polymorphisms have already been associated with inflammatory diseases such as inflammatory bowel disease, tuberculosis, and leprosy." (PMID 37063320, 2023). "A genome-wide association study has shown that LRRK2 is associated with inflammatory bowel disease (IBD) and Mycobacterium leprae infection." (PMID 32164260, 2020). "The link of LRRK2 to innate immune inflammatory pathways is further strengthened by findings that LRRK2 polymorphisms also enhance the risk of developing inflammatory bowel disease." (PMID 32210756, 2020). "LRRK2 appears to be closely linked to inflammatory bowel disease (IBD), which is a chronic inflammatory condition of the digestive tube that includes Crohn’s disease (CD) and ulcerative colitis (UC)." (PMID 32410948, 2020). "LRRK2 knock-outs in mouse models, displays phenotypes of hyperactive immune responses and increased risk to inflammatory bowel disease by regulating the transcriptional regulatory protein nuclear factor of activated T cells." (PMID 31217489, 2019). "Additional genetic studies, most notably genome-wide association studies (GWAS) have revealed the association of variants at the LRRK2 locus with inflammatory bowel disease, Leprosy and PD." (PMID 30223621, 2018). "Rare mutations in the LRRK2 gene cause familial Parkinson’s disease (PD) and inflammatory bowel disease." (PMID 30223621, 2018). "LRRK2, the most frequently associated hidden node across the datasets, has indeed been associated with inflammatory bowel disease as well as kidney injury." (PMID 29258445, 2017). "In fact LRRK2, a major susceptibility gene for inflammatory bowel disease (IBD), was found to recruit Rab2 to ISGs for the selective sorting of lysozyme during SG maturation in Paneth cells." (PMID 27751232, 2016). "Dysfuntion in autophagy genes such as ATG16L1, IRGM, and LRRK2, are emerging as potential susceptibility traits in patients with inflammatory bowel disease." (PMID 22363587, 2012). "Notably, variability in the LRRK2 locus is also associated with inflammatory bowel disease, pediatric immune disorders, and type-1 response in leprosy." (PMID 39062657, 2024). "This has led to LRRK2 sometimes being reported as a risk factor for inflammatory bowel disease, even though linkage is stronger (and may be specific) to CD." (PMID 31864390, 2019). "As a common risk gene for PD and inflammatory bowel disease (IBD), LRRK2 suggests a close connection between the brain and intestines." (PMID 39500355, 2024). "Genomewide association studies have identified LRRK2 as a risk factor for peripheral inflammatory responses in leprosy infection, bacterial infection and inflammatory bowel disease (IBD)." (PMID 38725082, 2024). "Therefore, it was speculated that the same LRRK2 gene that is also associated with inflammatory bowel disease may modulate inflammatory pathways related to neurodegeneration." (PMID 35674870, 2022). "Mutations in leucine-rich repeat kinase 2 (LRRK2) comprise a common genetic risk factor for Parkinson’s disease (PD) and inflammatory bowel disease (IBD)." (PMID 35126095, 2021). "As a matter of fact, in various illnesses associated with gastrointestinal tract disturbances, such as inflammatory bowel disease (IBD) and ulcerative colitis, several PD-risk genes, such as LRRK2 and caspase recruitment domain-containing protein 15 (CARD15), are shared." (PMID 36139483, 2022). "LRRK2 function extends beyond the brain; it is involved in inflammatory bowel diseases, infections, and cancers." (PMID 33057020, 2020).
inflammatory bowel disease (continued). "Besides PD, mutations in the LRRK2 gene are also found in immune-related disorders, such as inflammatory bowel disease (IBD) and some bacterial infections." (PMID 32674367, 2020). "Although it has been reported that the kinase activity of LRRK2 has some association with the pathogenesis of PD, inflammatory bowel disease (IBD), and some bacterial infections, its true function remains unclear." (PMID 32164260, 2020). "LRRK2 can be physically associated with NRON and this protein-RNA complex has been proven to be a NFAT suppressor in many inflammatory diseases such as inflammatory bowel disease, and LRRK2 deficiency can lead to a more serious inflammation response." (PMID 29545945, 2018). "Interestingly, several genome-wide association studies (GWAS) have identified that the LRRK2 gene is a common susceptibility locus for both PD and Crohn’s disease (CD), one of the inflammatory bowel diseases (IBD) that causes chronic inflammation of the gastrointestinal (GI) tract." (PMID 33750819, 2021). "A firm link between LRRK2 function and the immune system is emerging, with several lines of evidence suggesting a role in microglial and macrophage inflammatory responses, host response to pathogens as well as inflammatory bowel disease." (PMID 23799078, 2013). "Aberrant activation of LRRK2 can also contribute to intestinal inflammation, mainly in inflammatory bowel disease (IBD)." (PMID 41977401, 2026). "Strikingly, growing evidence supports the role of LRRK2 in inflammation and the onset of inflammatory diseases such as Crohn’s disease, an inflammatory Bowel disease (IBD) and patients with IBD are more likely to develop PD." (PMID 35874822, 2022). "Indeed, the connection between LRRK2 and CD forms part of a body of evidence that has been used to create a theory that PD may be a low-grade inflammatory bowel disease." (PMID 31864390, 2019). "In humans, polymorphisms in several autophagy-related genes, including IRGM, LRRK2, SMURF1 and ATG16L1, leading to autophagy deficiency are linked to inflammatory bowel disease (IBD) susceptibility." (PMID 28916785, 2017).
Cognitive impairment (51 papers, 2008 to 2026). Abnormal cognition is characterized by deficits in thinking, reasoning, or remembering. "Carriage of APOE E4 variants increases the risk of cognitive impairment in PD, whereas the LRRK2 p.G2019S variant reduces the risk of hallucinations and dementia." (PMID 40926580, 2025). "The phenotype is similar in individuals carrying either one or two LRRK2 G2019S mutations and, in general, both homozygous and heterozygous mutations are associated with low rates of cognitive impairment and psychiatric co-morbidity." (PMID 39175765, 2024). "For example, cognitive decline affects 70% of PD patients with pathogenic alpha-synuclein (SNCA) gene variants, while only 23% of Leucine-Rich Repeat Kinase 2 (LRRK2) carriers exhibit cognitive impairment." (PMID 38020640, 2023). "LRRK2 G2019S mutation in patients with PD has been linked to both motor and cognitive impairments, and G2019S mutation impaired dopamine homeostasis in mouse and Caenorhabditis elegans models." (PMID 37269951, 2023). "Cognitive impairment has been well established in Mn toxicity, and LRRK2 G2019S mutation has also been associated with dementia." (PMID 37269951, 2023). "Meanwhile, after SD, LRRK2 deficiency aggravated cognitive impairments, especially in the recall memory cued by fear conditioning test." (PMID 36138936, 2022). "People with A53T mutations develop an early onset aggressive form associated with cognitive impairment whilst those with LRRK2 mutations had less severe deficits in cognition and olfaction compared to idiopathic PD." (PMID 36551782, 2022). "Cognitive impairment in PD associated with LRRK2 mutations is the most studied NMS, and existing evidence suggests that dementia is uncommon in these patients even one or two decades after the onset of the disease." (PMID 33763016, 2021). "More studies are needed, but what has been published to date suggests that cognitive impairment is less frequent in LRRK2-PD, more specifically in PD associated with the R1441G mutation." (PMID 33763016, 2021). "Several studies and reviews suggest that LRRK2 mutations are associated with a more benign disease course, less severe clinical symptoms, lower risk of cognitive impairment and better cognitive performance." (PMID 31324919, 2019). "Such suggestions are relevant mainly for people at putatively high risk of developing AD (i.e., older adults with mild cognitive impairment subtypes) or PD (i.e., older adults with either Mild Parkinsonian signs or LRRK2 G2019S mutation)." (PMID 28588547, 2017). "A research reported two LRRK2 mutation carriers who showed cognitive impairment, leading to clinical diagnoses of corticobasal syndrome (CBS) and primary progressive aphasia (PPA), a subtype of frontotemporal dementia (FTD)." (PMID 25391693, 2014). "A more comparable measure is the proportion of patients who develop cognitive impairment within 2 years of symptom onset: 6 patients (3·4%) with mutations in LRRK2 compared with 48 patients (9·8%) with idiopathic PD (p=0·0016)." (PMID 18539534, 2008). "The mean disease duration of patients with cognitive impairment was 15·2 years (SD 5·9 years) for those with mutations in LRRK2 and 14·4 years (SD 5·9 years) for those with idiopathic PD." (PMID 18539534, 2008). "Indeed, increased phosphorylation of Rab10 was observed in the urine EVs of patients with PD with LRRK2 mutations compared to controls, and it further correlated with the patients’ motor and cognitive impairment scores." (PMID 39337560, 2024). "Other variants of the LRRK2 mutation, such as G2385R, also displayed sex-related phenotypes differences, with male carriers of G2385R having a lower risk of cognitive impairments (p = 0.003) and female G2385R carriers displaying a lower risk of autonomic dysfunction (p = 0.04)." (PMID 37545736, 2023). "Besides, recent studies indicated that GBA-PD and SNCA-PD experienced more severe cognitive impairment, whereas those with LRRK2 mutation had milder symptoms." (PMID 37699957, 2023).
Cognitive impairment (continued). "More sensitive examinations are necessary to detect cognitive function and to determine whether the PIGD motor phenotype is associated with cognitive impairment in LRRK2 variants carriers." (PMID 27330837, 2016). "As LRRK2 is the most common genetic cause for PD, it has drawn great interest concerning whether cognitive impairments in PD are related with LRRK2." (PMID 26346174, 2015). "Moreover, comparing with patients with idiopathic PD patients, patients with LRRK2 G2019S had a lower risk of cognitive impairment and hyposmia." (PMID 25391693, 2014). "Non-motor symptoms generally occurred at similar frequencies in patients with LRRK2 Gly2019Ser to those reported for patients with idiopathic PD; however, patients with LRRK2 Gly2019Ser had a lower risk of cognitive impairment and hyposmia than did patients with idiopathic PD." (PMID 18539534, 2008). "Cognitive impairment could be associated with multiple brain regions including the cortex and hippocampus, requiring further research to determine regional-specific effects of Mn-LRRK2 pathology associated with behavioral deficits." (PMID 37269951, 2023). "Interestingly, elevated levels of Ser(P)-1292 LRRK2 were found in both urinary and CSF exosomes derived from PD patients carrying an LRRK2 mutation compared to controls, and the levels of LRRK2 autophosphorylation correlated with the severity of cognitive impairment." (PMID 31450727, 2019). "They found that elevated levels of Ser(P)-1292 LRRK2 and higher levels of pT73-Rab10—a substrate of LRRK2 kinase—in EVs correlate with cognitive impairment, difficulty in daily activities, and worse disease progression in idiopathic PD." (PMID 39337560, 2024). "It is reported that LRRK2 G2019S knock-in mice successfully mimic the neuronal pathology in striatum and cognitive impairments, further contributing to our understanding of the broader impact of PD on cognitive functions." (PMID 38765773, 2024). "Mutations in the leucine-rich repeat kinase 2 (LRRK2) and parkin RBR E3 ubiquitin protein ligase genes are thought to be protective against cognitive impairment and ocular disturbances." (PMID 37626529, 2023). "Taken together, our findings demonstrate that Mn-induced motor deficits and cognitive impairment were further exacerbated in G2019S mice, possibly via hyper-kinase activity of LRRK2." (PMID 37269951, 2023). "Our findings provide insights into the physiological role of LRRK2-mediated pathways in regulating microglial synaptic pruning with respect to modulating SD-related cognitive disorders." (PMID 36138936, 2022). "Elevated leucine-rich repeat kinase 2 (LRRK2) mutations in urine have recently been linked to idiopathic PD and the intensity of cognitive impairment." (PMID 35902981, 2022). "Cognitive impairment is higher in GBA- and SNCA-associated PD, lower in Parkin- and PINK1-PD, and possibly milder in LRRK2-PD." (PMID 35003622, 2021). "LRRK2-PD patients exhibited less frequently subjective cognitive complaints and mild cognitive impairment or dementia." (PMID 33763016, 2021). "Among LRRK2-PD patients, the frequency of cognitive impairment is similar or lower than that observed in IPD." (PMID 35003622, 2021). "The physical interaction between LRRK2 and eight proteins with documented mutations linked to intellectual disability is further evidence to support the role of LRRK2 in cognitive impairment." (PMID 31963867, 2020). "Other reports described more specific clinical features in LRRK2 carriers such as a lower limb onset, more hallucinations, behavioral disorders, and dopaminergic dysregulation syndrome but less cognitive impairment." (PMID 28465860, 2017). "Indeed, cognitive impairment is higher in GBA- and SNCA-associated PD, lower in Parkin- and PINK1-PD, and possibly milder in LRRK2-PD." (PMID 39519043, 2024).
Cognitive impairment (continued). "Furthermore, a relationship was shown between the degree of cognitive impairment and Ser(P)-1292 LRRK2 levels in urine exosomes, highlighting the importance of this protein in the pathophysiology of PD." (PMID 39431275, 2024). "The present studies demonstrate that Mn exposure in WT mice induced motor deficits, cognitive impairment, and dopaminergic dysfunction in the nigrostriatal pathway with a concomitant increase in LRRK2 and TNF-α protein levels in the basal ganglia, which were further exacerbated in LRRK2 G2019S mice." (PMID 37269951, 2023). "Consistent with this, following TBI, increased LRRK2 expression has been observed to be associated with increased hypoxia-inducible factor 1-α (HIF-1α), while inhibition of LRRK2 reduced neurodegeneration, neuroinflammation and cognitive deficits." (PMID 38026695, 2023). "Our findings evidence that LRRK2 modulates REM/NREM sleep and its deficiency may exacerbate sleep deprivation-related cognitive disorders by perturbing synaptic plasticity and microglial synaptic pruning in mice." (PMID 36138936, 2022). "Importantly, our results further demonstrate that after SD, LRRK2 knockout can alter the dendritic spinal integrity, synaptic density, and synapse-related signaling, and lead to synaptic dysfunction and cognitive impairment." (PMID 36138936, 2022). "It has been demonstrated that some nonmotor symptoms in MDS‐UPDRS I, like cognitive impairment and autonomic dysfunction, can precede dopamine transporter deficit in nonmanifesting LRRK2 mutation carriers." (PMID 35934920, 2022). "In male sex, LRRK2 G2385R carriers showed lower risk in cognitive impairment compared with non-carriers (OR = 0.301, p = 0.003, 95%CI 0.135–0.668)." (PMID 33771108, 2021). "However, interestingly, cognitive impairment and dementia are correlated with the presence of Lewy pathology in LRRK2-PD." (PMID 35003622, 2021). "Lewy pathology in LRRK2-PD associates with increased non-motor symptoms such as cognitive deficits, anxiety, and orthostatic hypotension." (PMID 34749824, 2021). "To further support our hypothesis that LRRK2 is a candidate gene for cognitive impairment, we examined the transcript levels of both LRRK2 and MUC19 in human tissues." (PMID 31963867, 2020). "The control with the LRRK2 p.G2019S mutation has neither motor alteration nor cognitive impairment at the age of 77 yrs, and had no family history of PD." (PMID 26600626, 2015). "Although there is no existing study regarding the correlation of nonmotor features and LRRK2 S1647T, some similar reports on relationships between cognitive impairment and LRRK2 polymorphisms in other loci reached different conclusions." (PMID 26346174, 2015). "After adjusting age, disease duration and schooling year, we found that males with LRRK2 G2385R carriers showed lower risk in cognitive impairment (OR = 0.301, p = 0.003) as compared with males without LRRK2 G2385R non-carriers and the association remained significant after Bonferroni correction." (PMID 33771108, 2021). "Carriers of the G2019 variant in LRRK2 and PRKN mutations showed sustained advantages in motor complications and activities of daily living, whereas GBA mutation carriers frequently developed cognitive impairment and stimulation-resistant symptoms within 2 to 7 years after surgical treatment." (PMID 30707228, 2019). "Our results suggest LRRK2 G2019S PD appears to be a slowly progressive predominantly motor subtype of PD with a lower prevalence of hyposmia, RBD and cognitive impairment." (PMID 38804604, 2024). "Similarly, patients with LRRK2 mutations often have prominent prodromal gait deficits, and LRRK2 carriers with synuclein pathology exhibit more cognitive impairment, anxiety, and orthostatic hypotension than those without which will likely have a different prodromal state." (PMID 32457695, 2020).
Cognitive impairment (continued). "Consistent with previous studies, our analysis showed greater cognitive impairment in patients with GBA-PD than iPD, while LRRK2-PD demonstrated more preserved cognitive functions." (PMID 31164863, 2019). "Here we report that aged LRRK2 mutant rats develop progressive motor dysfunction which is reversed by l-DOPA, and cognitive deficits, along with impaired striatal dopamine release and alterations in the firing properties of dopaminergic SNc neurons." (PMID 26744332, 2016). "Cognitive impairment varies across sporadic Parkinson's disease (PD) and the common genetic subtypes glucocerebrosidase (GBA1) and leucine-rich repeat kinase 2 (LRRK2) PD and is influenced by Apolipoprotein E (APOE) polymorphisms and Alzheimer's disease (AD) co-pathology." (PMID 41730900, 2026). "Though motor features were similar among LRRK2 PD cases with and without Lewy body pathology, non-motor features, including orthostatic hypotension, anxiety and cognitive impairment, were more frequent in the Lewy body group." (PMID 39175765, 2024). "We also found that male sex among LRRK2 G2385R non-carriers had a tendency to develop cognitive impairment." (PMID 33771108, 2021). "There is a trend to more cognitive impairment in LRRK2 G2019S carriers than noncarriers but the difference is not significant (p = 0.059)." (PMID 28465860, 2017). "In our study, LRRK2 carriers have a trend to more cognitive impairment that was not confirmed in the logistic regression model." (PMID 28465860, 2017). "All three LRRK2-PD patients with RBD were men, carried the G2019S mutation, had the postural instability and gait difficulty motor subtype, no hallucinations, no cognitive impairment and lack of a previous history of impulse control disorders." (PMID 26177462, 2015).